PHOX2B (paired like homeobox 2B)
Diseases named in the same sentence as PHOX2B in open-access papers (continued):
Sharing a sentence is not in itself a finding about the gene and the disease.
CHARGE syndrome (2 papers, 2023 to 2024). CHARGE syndrome is a multiple congenital anomaly syndrome characterized by the variable combination of multiple anomalies, mainly Coloboma; Choanal atresia/stenosis; Cranial nerve dysfunction; Characteristic ear anomalies (known as the major 4 C's). "As PHOX2B is involved in neural crest development, similar to CHD7, the loss of PHOX2B function can lead to respiratory issues resembling those in patients with CHARGE syndrome." (PMID 38892128, 2024). "By investigating the roles of CHD7 and PHOX2B in CHARGE, we have furthered our understanding of disease pathogenesis, with the overall goal of making anesthesia a safer process in individuals with CHARGE syndrome." (PMID 37239446, 2023).
ganglioneuroblastoma (2 papers, 2018 to 2022). A neuroblastic tumor characterized by the presence of neuroblastic cells, ganglion cells, and a stroma with Schwannian differentiation constituting more than fifty-percent of the tumor volume. "Diffuse expression of PHOX2B is a characteristic feature of peripheral neuroblastoma, and its expression is reduced with more cellular differentiation, a feature that was observed in cases 31 (post‐treatment) and 34 (ganglioneuroblastoma)." (PMID 35763016, 2022).
hyperinsulinism (2 papers, 2023 to 2025). Abnormally high levels of insulin in the blood. "Most of the patients had a typical polyalanine expansion mutation in the PHOX2B gene as usually found in CCHS without hyperinsulinism." (PMID 37065762, 2023).
Hypoglycemia (2 papers, 2021 to 2025). A decreased concentration of glucose in the blood. "We report a four-month-old female with genetically confirmed PHOX2B polyalanine repeat expansion (c.726_764dup; p.Ala248_Ala260dup; 33 repeats) who developed recurrent, symptomatic postprandial hypoglycemia after transitioning from continuous enteral feeding to oral bolus feeds." (PMID 41531556, 2025).
lymphoma (2 papers, 2022 to 2025). A malignant (clonal) proliferation of B- lymphocytes or T- lymphocytes which involves the lymph nodes, bone marrow and/or extranodal sites. "Two mice in the combination therapy group ultimately died from thoracic tumors, of which 1 was a PHOX2B+ thoracic neuroblastoma (suggesting a metastatic or primary thoracic neuroblastoma) and the other a PHOX2B–MYCN–CD45+CD3+ lymphoma." (PMID 35943801, 2022).
Nephroblastoma (2 papers, 2017 to 2019). An embryonal neoplasm characterized by the presence of epithelial, mesenchymal, and blastema components. "Although we found the correlation between PHOX2B rs28647582 T>C polymorphism and Wilms tumor susceptibility in stratified analysis, some limitations existed in our study." (PMID 31652452, 2019). "The association between the PHOX2B rs28647582 T>C polymorphism and Wilms tumor susceptibility was assessed by odds ratios (ORs) and 95% confidence intervals (CIs)." (PMID 31652452, 2019). "It was difficult to discover the genuine association between PHOX2B rs28647582 T>C polymorphism and Wilms tumor." (PMID 31652452, 2019). "We observed that PHOX2B rs28647582 TC/CC genotypes significantly increased Wilms tumor susceptibility in subgroups older than 18 months or clinical stages III+IV." (PMID 31652452, 2019). "In conclusion, we have exposed that PHOX2B rs28647582 T>C polymorphism is weakly associated with Wilms tumor susceptibility." (PMID 31652452, 2019). "Our study suggested that PHOX2B rs28647582 T>C was weakly associated with Wilms tumor susceptibility." (PMID 31652452, 2019). "Therefore, we conducted a case-control study involving 145 Wilms tumor patients and 531 controls to explore the association between the PHOX2B rs28647582 T>C polymorphism and Wilms tumor susceptibility." (PMID 31652452, 2019). "This is the first investigation about PHOX2B rs28647582 T>C polymorphism and Wilms tumor." (PMID 31652452, 2019). "Considering this polymorphism may affect the differentiation of posterior renal blastocyst, we conducted this experiment about PHOX2B rs28647582 T>C polymorphism and Wilms tumor susceptibility." (PMID 31652452, 2019). "Finally, this paper merely revealed the connection between PHOX2B rs28647582 T>C polymorphism and Wilms tumor susceptibility." (PMID 31652452, 2019). "In addition, PHOX2B rs28647582 T>C polymorphism may combine with tumor-related genes to modify Wilms tumor susceptibility." (PMID 31652452, 2019). "Our results indicated that PHOX2B rs28647582 T>C polymorphism did not significantly alter Wilms tumor susceptibility." (PMID 31652452, 2019). "The association between PHOX2B single nucleotide polymorphisms (SNPs) and Wilms tumor risk has not been investigated." (PMID 31652452, 2019).
paraganglioma (2 papers, 2022 to 2025). A benign or malignant neoplasm arising from paraganglia located along the sympathetic or parasympathetic nerves. "PHOX2B is considered highly specific for the peripheral autonomic nervous system, and diffuse strong nuclear immunoreactivity for PHOX2B has been established as a reliable marker for peripheral neuroblastoma and paraganglioma." (PMID 35763016, 2022). "Both paraganglioma and panNETs with paraganglioma-like morphology show S100-positive sustentacular cells complicating the differential diagnosis, which is mainly based on the lack of low weight cytokeratins positivity and GATA3, tyrosine hydroxylase, PHOX2B, and Hand2 expression in the former." (PMID 40668487, 2025).
Rett-like syndrome (2 papers, 2021 to 2023).
autonomic disorders (1 paper, 2021). "In this manuscript we have reported a PHOX2B variant screening performed in Italian IALTE and SUID/SIDS patients to search for genetic elements predisposing to these autonomic disorders, whose sudden manifestation may resemble CCHS, caused by PHOX2B mutations." (PMID 33815256, 2021).
autonomic dysfunction (1 paper, 2021). "The novel heterozygous mutation c.780dupT on PHOX2B gene is associated with more ventilation dependency and autonomic dysfunction, predicting a more severe phenotype." (PMID 33855005, 2021).
brain tumors (1 paper, 2022). "The biological basis for PHOX2B immunoexpression in primary brain tumors, and the reason for its association with specific tumor types (i.e., ETMR and pineoblastoma) is unclear." (PMID 35763016, 2022).
Central hypothyroidism (1 paper, 2022). A type of hypothyroidism due to an insufficient stimulation of an otherwise normal thyroid gland. "Here, we report the case of a 5-year-old girl with suspected ROHHAD, with rapid weight gain, breathing cessation, decreased height, hypoventilation, central hypothyroidism, hyperprolactinemia, and absolute deficiency of growth hormone, and negative PHOX2B sequencing results." (PMID 36120657, 2022).
cervix carcinoma (1 paper, 2010). "ALK, PHOX2B and PHOX2A resulted to be highly expressed in almost all analyzed NB cell lines with respect to a pool of normal tissues and to HeLa cells, a cervix carcinoma cell line characterized by low level of ALK expression and almost undetectable expression levels of the two PHOX2 genes." (PMID 20957039, 2010).
CNS embryonal tumor (1 paper, 2022). "In our study, PHOX2B positivity was also noted in a single unusual case of CNS embryonal tumor NEC (a HGNET with PLAGL2 amplification)." (PMID 35763016, 2022).
cone-rod dystrophy (1 paper, 2025). Inherited retinal dystrophies that belong to the group of pigmentary retinopathies. "In contrast, a CRX E42A variant associated with cone rod dystrophy was found to disrupt cooperativity and behaved similarly as the PHOX2B E42Q and ALX4 E42A variants." (PMID 41279221, 2025).
congenital myasthenic syndrome (1 paper, 2021). Congenital myasthenic syndrome (CMS) is a group of genetic disorders of impaired neuromuscular transmission at the motor endplate characterized by fatigable muscle weakness. "Genetic tests for common causes of neonatal hypotonia (spinal muscular atrophy, Prader–Willi syndrome, myotonic dystrophy), congenital myasthenic syndrome and central hypoventilation syndrome (PHOX2B polyalanine expansion mutations) were normal." (PMID 34285383, 2021).
Crohn disease (1 paper, 2022). A gastrointestinal disorder characterized by chronic inflammation involving all layers of the intestinal wall, noncaseating granulomas affecting the intestinal wall and regional lymph nodes, and transmural fibrosis. "For instance, two enteroendocrine markers, ubiquitination factor E4A (UBE4A) and paired-like homeobox 2b (Phox2B), are reported to significantly augment the distal ileum of patients with Crohn’s disease." (PMID 35050153, 2022).
Down syndrome (1 paper, 2017). "This does not come as a total surprise, as several known HSCR genes (e.g., KBP, SOX10, NRG1, IKBKAP, ZEB2, PHOX2B) are involved in both CNS and ENS pathologies and the fact that HSCR is strongly associated with Down syndrome." (PMID 28274275, 2017).
embryonal tumors (1 paper, 2022). "Care should be taken in the interpretation of focal PHOX2B positivity in any differential diagnosis including CNS embryonal tumors, especially in a small volume sample." (PMID 35763016, 2022). "Among CNS embryonal tumors, focal immunoreactivity for PHOX2B was observed in most (5/7) embryonal tumors with multilayered rosettes (ETMR) and a single high‐grade neuroepithelial tumor (HGNET) with PLAGL2 amplification; the remaining 27 CNS tumors were essentially immunonegative (<0.05% positive)." (PMID 35763016, 2022). "PHOX2B expression focally exceeding 20%–30% of cells can be observed in ETMR, and focal PHOX2B expression in a subset of tumor cells was observed in a single case of CNS embryonal tumor NEC (HGNET with PLAGL2 amplification)." (PMID 35763016, 2022).
Encephalopathy (1 paper, 2023). Encephalopathy is a term that means brain disease, damage, or malfunction. "Together, these results suggest that disruption of Kcnq2 channel function in Phox2b-expressing neurons disrupts central chemoreception and may contribute to breathing problems associated with Kcnq2 encephalopathy." (PMID 38052789, 2023).
gastrointestinal stromal tumor (1 paper, 2017). "The TF obtained commonly for COAD, PHOX2B, is related to TLX2, a gene which has been shown to play a role in the tumorigenesis of gastrointestinal stromal tumors." (PMID 28347313, 2017).
gastroparesis (1 paper, 2026). Paralysis of the muscles of the stomach wall resulting in delayed emptying of the gastric contents into the small intestine. "The importance of this gut-brain axis is illustrated by mutations in Phox2b, which lead to a wide range of pathological conditions e.g., gastroparesis, heart failure, impaired respiratory control." (PMID 40975751, 2026).
glioma (1 paper, 2011). A benign or malignant brain and spinal cord tumor that arises from glial cells (astrocytes, oligodendrocytes, ependymal cells). "More importantly, the methylation levels of the ANKDD1A and PHOX2B promoters tended to be negatively correlated with age and the differentiation grades of human glioma." (PMID 21962230, 2011). "The methylation levels of seven gene promoters (ANKDD1A, GAD1, SIX3, SST, PHOX2B, PCDHA8, and HIST1H3E) in glioma patients and cell lines were significantly higher than those in non-tumor controls (p < 0.01)." (PMID 21962230, 2011). "Eight promoter-hypermethylated genes (ANKDD1A, GAD1, HIST1H3E, PCDHA8, PCDHA13, PHOX2B, SIX3, and SST) were confirmed in primary glioma and cell lines." (PMID 21962230, 2011). "In addition, we found that the percentages of promoter methylation in the ANKDD1A and PHOX2B, but not the GAD1, HIST1H3E, PCDHA8, PCDHA13, SIX3 and SST, were associated negatively with the differentiation degrees of human gliomas." (PMID 21962230, 2011).
hereditary cancer (1 paper, 2025). Malignant neoplasms occurring in families at a rate greater than that expected by chance and caused by germline mutations in a specific gene. "LP/P findings in pleiotropic genes linked to human development and hereditary cancer (TSC1, PHOX2B, WT1, SPRED1, NF1, LZTR1, HOXB13) were identified in several patients with syndromic phenotypes." (PMID 40060932, 2025).
influenza (1 paper, 2023). An acute viral infection of the respiratory tract, occurring in isolated cases, in epidemics, or in pandemics; it is caused by serologically different strains of viruses (influenzaviruses) designated A, B, and C, has a 3-day incubation period, and usually lasts for 3 to 10 days. "Influenza infection induced PGE2 to similar levels in plasma and BALF of Gabra1-IRES-cre; Ptger3flox, Phox2b-cre; Ptger3flox, Advillin-creER; Ptger3flox and Ptger3flox mice, consistent with changes in PGE2 detection rather than PGE2 synthesis underlying the observed behavioural differences." (PMID 36890237, 2023).
MALT lymphoma (1 paper, 2020). An indolent, extranodal type of non-Hodgkin lymphoma composed of small B-lymphocytes (centrocyte-like cells). "Sanger sequencing of germline DNA revealed the presence of a mutant base T of PHOX2B and a mutant base C of ADCY1 in the sequence, which were discovered for the first time in MALT lymphomas involving the kidney." (PMID 33585230, 2020).
medulloblastoma (1 paper, 2021). A malignant, invasive embryonal neoplasm arising from the cerebellum. "The pathogenic roles of PHOX2B mutations have been published in the ClinVar database, but few reports exist on de novo germline mutations associated with childhood medulloblastoma development." (PMID 33468206, 2021). "We present an 11-year-old male with medulloblastoma, who harbors a de novo PHOX2B germline mutation as detected by whole exome sequencing (WES)." (PMID 33468206, 2021). "This case revealed a de novo PHOX2B germline mutation as a potential cause of medulloblastoma in a child and suggests familial germline variant screening is useful when an affected family is considering having a second child." (PMID 33468206, 2021). "In this case, we reported a de novo PHOX2B germline mutation as a potential cause of medulloblastoma in a child." (PMID 33468206, 2021). "Here, we identified the c.765_779del deletion of PHOX2B in a patient with medulloblastoma and confirmed that the mutation existed in other tissues from the patient." (PMID 33468206, 2021). "By using whole exome sequencing (WES, the NovaSeq 6000 Sequencing System, Illumina) technology and Sanger sequencing validation, we report the case of a child with a de novo c.765_779 deletion of PHOX2B as a contributor to the risk of medulloblastoma." (PMID 33468206, 2021). "Further biomolecular studies on PHOX2B are necessary for better understanding its pathogenic role in medulloblastoma." (PMID 33468206, 2021). "Founder germline mutation of PHOX2B that cause childhood medulloblastoma are even more rare." (PMID 33468206, 2021).
metastatic cancer (1 paper, 2017). A carcinoma which has spread from the original site of growth to another anatomic site. "Therefore, PHOX2B gene down-regulation in the early phase of tumorigenesis may affect tumor differentiation and growth, without affecting the late metastatic cancer stage." (PMID 29069774, 2017).
Obesity (1 paper, 2025). Accumulation of substantial excess body fat. "A total of 26 children started with HMV because of CCHS due to PHOX2B mutation (n = 19), Rapid-onset Obesity with Hypothalamic dysfunction Hypoventilation and Autonomic Dysregulation (ROHHAD) (n = 3) or an elusive diagnosis (n = 4)." (PMID 41148358, 2025).
Ondine syndrome (1 paper, 2020). "The PHOX2B polyalanine repeat mutation has also been identified in HD associated with Ondine’s syndrome." (PMID 31916119, 2020).
pheochromocytoma (1 paper, 2012). "Among these, the significance of paired-like homeobox 2b in pheochromocytoma has not been reported previously." (PMID 23106811, 2012).
Prader-Willi syndrome (1 paper, 2022).
respiratory depression (1 paper, 2014). A decrease in ventilation secondary to impaired signals from the central nervous system. "The loss of RTN neurons leads to respiratory depression in vivo and in vitro, and RTN Phox2b neurons have been a leading candidate for an independent respiratory oscillator driving abdominal and, possibly, VII motor output." (PMID 24842997, 2014).
Sepsis (1 paper, 2025). Sepsis is defined as life-threatening organ dysfunction caused by a dysregulated host response to infection. "Differential analysis identified 6 proteins that were significantly upregulated in sepsis serum samples, including MMP9, lipocalin-2 (LCN2), serum amyloid A1 (SAA1), serum amyloid A2 (SAA2), paired-like homeobox 2B (PHOX2B), and lactoferrin (LTF) (|log2FC| > 1, P < 0.05)." (PMID 41306770, 2025).
small cell lung carcinoma (1 paper, 2021). Small cell lung cancer (SCLC) is a highly aggressive malignant neoplasm, accounting for 10-15% of lung cancer cases, characterized byrapid growth, and early metastasis. "Finally, we show that SMAD3, ZNF217, KLF13, GATA2, GATA3, KLF7, and PHOX2B are components of CRCs in other cancers, including DLBCL, pancreatic, gastric, breast, and small cell lung cancer." (PMID 35201514, 2021).
tauopathy (1 paper, 2023). Neurodegenerative disorders involving deposition of abnormal tau protein isoforms (tau proteins) in neurons and glial cells in the brain. "Unlike CCHS however where there is genetic (developmental) mutation/deactivation of the PHOX2B gene, we suspect in this tauopathy model, loss of chemoreflex function occurs late in life." (PMID 37811498, 2023).
viral infection (1 paper, 2024). "We identified RTN neurons by the mRNA expression of the neuropeptide NMB and observed a reduced number in both total Nmb and Nmb+/PHOX2B+ neurons in PHOX2B shRNA-treated rats compared to naive and NT-shRNA rats two weeks after viral infection." (PMID 38727716, 2024). "Two weeks after viral infection, we observed a modest reduction of PHOX2B/Nmb expressing neurons in the RTN but no significant changes in basal VE or in the CO2 chemoreflex." (PMID 38727716, 2024).